HIF1A (hypoxia inducible factor 1 subunit alpha)
Diseases named in the same sentence as HIF1A in open-access papers (continued):
Sharing a sentence is not in itself a finding about the gene and the disease.
pulmonary fibrosis (continued). "This study seeks to evaluate the therapeutic potential of targeting glycolysis, FAO, and HIF‐1α in silica‐induced pulmonary fibrosis, thus highlighting the potential of HIF‐1α‐mediated metabolic dysregulation as a promising therapeutic target for experimental pulmonary fibrosis." (PMID 39721015, 2025). "In addition to HIF-1α, previous studies have also implicated HIF-2α in the pathogenesis of pulmonary fibrosis." (PMID 41344160, 2025). "Furthermore, fibrosis resulting from this oxidative hypoxia leads to localized tissue hypoxia, further perpetuating HIF-1α stabilization and reinforcing a pathological cycle of pulmonary fibrosis." (PMID 41344160, 2025). "Resveratrol, on the other hand, may mitigate bleomycin-induced pulmonary fibrosis by inhibiting HIF-1α and NF-κB expression." (PMID 38178024, 2024). "Additionally, HIF-1α regulated EMT in paraquat intoxication-induced early lung fibrosis through HIF-1α via the Snail and β-catenin pathways." (PMID 37762310, 2023). "Furthermore, the lactate/GPR81/HIF1α pathway can mediate hypoxia-induced idiopathic pulmonary fibrosis." (PMID 38136207, 2023). "Hypoxia-inducible factor-1α (HIF-1α) regulates a variety of pathological processes, for example, it can facilitate the epithelial to mesenchymal transition through activating Lox in paraquat-induced pulmonary fibrosis." (PMID 38031108, 2023). "Therefore, our results suggest that inositol alleviates pulmonary fibrosis by promoting autophagy via inhibiting the EMT process mediated by the HIF-1α-SLUG axis in ARDS." (PMID 36589681, 2022). "The novel HIF-1α inhibitor, 2-methoxyestradiol (2-ME) could efficiently inhibit radiation-induced lung fibrosis in a preclinical study." (PMID 34722630, 2021). "Then we overexpressed HIF-1α by AAV in Rg3-treated lung fibrosis animals." (PMID 33639908, 2021). "Furthermore, inhibition of HIF-1α, directly or indirectly, alleviates pulmonary fibrosis in the bleomycin-induced model." (PMID 34150851, 2021). "In this sense, we speculated that NEDD4L may regulate the progression of pulmonary fibrosis through the CTHRC1/HIF-1α signal axis." (PMID 34512149, 2021). "In order to further investigate dual effects of HUCMSCs via HIF-1α in the bleomycin-induced pulmonary fibrosis, we detected the expression levels of factors in the secretome of HUCMSCs in inflammatory stimulation condition (ICM-HUCMSCs) and common condition (CM-HUCMSCs)." (PMID 34868320, 2021). "To validate our speculation that NEDD4L may modulate pulmonary fibrosis through the CTHRC1/HIF-1α signal axis, we performed Pearson correlation analysis on 35 lung tissue of IPF and revealed the negative correlation between the expression of NEDD4L and CTHRC1." (PMID 34512149, 2021). "The results indicated that HIF-1α may play an important role in the stimulation of HUCMSC-CM for belomycin-induced pulmonary fibrosis." (PMID 34868320, 2021). "Furthermore, resveratrol alleviates bleomycin-induced pulmonary fibrosis by suppressing HIF-1α and NF-κB expression, indicating its potential as a promising therapeutic drug candidate." (PMID 33495418, 2021). "Our results verified that HIF-1α plays different effects in different periods of pulmonary fibrosis, which may be one of the reasons." (PMID 34868320, 2021). "Therefore, Ginsenoside Rg3 can slow down the progression of pulmonary fibrosis by inhibiting the nuclear localisation of HIF-1α." (PMID 33639908, 2021). "Here we found an abnormal expression of HIF-1α in bleomycin-induced pulmonary fibrosis." (PMID 33639908, 2021).
pulmonary fibrosis (continued). "Moreover, hypoxia via HIF-1α contributes to the development and progression of pulmonary fibrosis through production of profibrotic factors HIF1α up-regulates the ADORA2B receptor on alternatively activated macrophages and contributes to pulmonary fibrosis." (PMID 31311941, 2019). "The activation of the HIF-1α pathway and subsequent EndoMT has been implicated in MCT- and CH-induced vascular remodeling and PH, as well as in the vascular pathology of pulmonary fibrosis and PAH in humans." (PMID 31877978, 2019). "Module 4 includes 34 genes, being associated with TNF and TCR signaling pathways and also involved in ER stress-related major (NF-kB survival signaling, lung fibrosis) and minor (AP-1 and HIF1α survival signaling, apoptosis, autophagy and inflammation) terms (green outlines)." (PMID 31523389, 2019). "In the present study, analysis of lung serial sections of bleomycin- induced pulmonary fibrosis in mice as well as UIP areas in lung biopsies undertaken for IPF diagnosis evidenced the co-expression of HIF-1α and CHOP in hyperplastic AECs covering the remodeled parenchymal air spaces." (PMID 30560874, 2018). "Our results suggest that the localized alveolar hypoxia or at least the stabilization of HIF-1α in AECs could trigger ER stress and related cell damages, thus contributing to the development of lung fibrosis." (PMID 30560874, 2018). "HIF-1α is elevated in pulmonary fibrosis and may contribute to disease progression, at least partially by inducing VEGF expression and subsequent collagen expression." (PMID 29045477, 2017). "To investigate the role of HIF‐1α in PQ poisoning‐induced early pulmonary fibrosis, we detected the level of HIF‐1α in PQ‐poisoned rat lung tissues and alveolar epithelial cells using real‐time quantitative PCR, Western blotting, immunofluorescence and immunohistochemistry." (PMID 26781174, 2016). "The aim of the present study was to confirm that HIF‐1α regulates EMT in PQ poisoning‐induced early pulmonary fibrosis and to further determine whether HIF‐1α modulates EMT via the Snail and β‐catenin pathways." (PMID 26781174, 2016). "Thus, we attempted to demonstrate that HIF‐1α regulated EMT in PQ poisoning‐induced early pulmonary fibrosis." (PMID 26781174, 2016). "The effects of TGF-β1 in pulmonary fibrosis is dependent on HIF-1α." (PMID 25723475, 2015). "Additionally, sustained high levels of HIF-1α over a long period of time may lead to the development of pulmonary fibrosis (PF)." (PMID 40710342, 2025). "In addition, HIF1a even could up-regulate the adora2b receptor on alternatively activated macrophages and contribute to pulmonary fibrosis." (PMID 33193637, 2020). "Therefore, HIF‐1α may be a therapeutic target for preventing the occurrence and progression of PQ poisoning‐induced pulmonary fibrosis in the early stage." (PMID 26781174, 2016). "Thus, we speculate that HIF‐1α regulates the process of EMT in PQ poisoning‐induced early pulmonary fibrosis." (PMID 26781174, 2016). "Experimental results confirmed that MOL000332 (n-coumaroyltyramine) significantly mitigated pulmonary fibrosis by suppressing the protein expression levels of EGFR, HIF1A, and GSK3B." (PMID 41847136, 2026). "By disrupting the pathological cycle of oxidative hypoxia while maintaining physiological HIF-1α regulation, ACF-2 has the potential to serve as the basis for future therapeutic approaches aimed at halting or even reversing pulmonary fibrosis." (PMID 41344160, 2025). "Further, the promotion of FAO, inhibition of glycolysis and HIF‐1α reduce ECM production and promote ECM degradation, ultimately impeding the progression of fibrosis and providing therapeutic relief for established pulmonary fibrosis in vivo." (PMID 39721015, 2025). "Our findings define a previously unrecognized mechanism by which NOX-derived ROS contribute to pulmonary fibrosis through PHD2 inactivation and HIF-1α hyperstabilization." (PMID 41344160, 2025).
pulmonary fibrosis (continued). "The promotion of FAO, inhibition of glycolysis and HIF‐1α reduce ECM production and promote ECM degradation, ultimately impeding the progression of fibrosis and providing therapeutic relief for established pulmonary fibrosis." (PMID 39721015, 2025). "Specifically, the mechanism involving the inhibition of Hif-1α-EGFR and its relation to ferroptosis in pulmonary fibrosis needs more exploration." (PMID 38584671, 2024). "Further analysis using the Kyoto Encyclopedia of Genes and Genomes suggested a crucial role for the Hif-1α-EGFR signaling pathway in ferroptosis and pulmonary fibrosis." (PMID 38584671, 2024). "In idiopathic pulmonary fibrosis (IPF) fibroblasts, 3% hypoxia induced different expression time courses for HIF-1α and HIF-2α." (PMID 36012260, 2022). "The findings suggest that HIF-1α induces EMT by promoting Snail transcription factor, which leads to pulmonary fibrosis." (PMID 35865337, 2022). "In the BLM-induced pulmonary fibrosis in rats, feitai blocked lung p38 MAPK, NF-κB65, HIF-1α, p-IκB-α, and TGF-β1 expression, and enhanced the Nrf2 and IkB expression." (PMID 35662950, 2022). "Our results suggest that inositol activates autophagy to inhibit EMT progression induced by the HIF-1α/SLUG signaling pathway in ARDS, and thereby alleviates pulmonary fibrosis." (PMID 36589681, 2022). "Our results showed that, compared with the silica group, the silica + KC7F2 group showed reduced expression of HIF-1α, COL1A1, α-SMA, and PSMAD3 and reduced lung fibrosis." (PMID 35682354, 2022). "In BLM-induced pulmonary fibrosis rats, KX-01 reduced pathological scores, collagen deposition, α-SMA, collagen I, collagen III, p-Src, HIF-1α, and p-STAT3." (PMID 34349652, 2021). "In the meantime, HIF-1α signaling has been found to play an essential role in EMT and lung fibrosis." (PMID 34722630, 2021). "Levels of succinate are up-regulated in lung myofibroblasts of patients with idiopathic pulmonary fibrosis, where they induce TGF-β1, hypoxia-inducible factor-1alpha (HIF-1a), and fibroblast differentiation." (PMID 33833766, 2021). "Among the numerous genes whose expression is regulated by TGFβ1 and HIF1α, PAI-1 has been shown to play a key role in pulmonary fibrosis development." (PMID 33805152, 2021). "HIF-1α and CAIX expression have also been shown to be upregulated in preclinical models of lung fibrosis, and chronic hypoxia was shown to worsen BLM-induced lung fibrosis in mice." (PMID 33580818, 2021). "The mechanism is attributed to the ability of ginsenoside Rg3 to reduce the nuclear localisation of HIF-1α and inhibit the evolution of EMT-related pulmonary fibrosis mediated by the TGF-β1/Smad3 signalling pathway." (PMID 33639908, 2021). "Elevated expression of HIF-1α in alveolar epithelial cells in bleomycin (BLM)-induced animal models and human pulmonary fibrosis indicates its involvement in the pathogenesis of this disease." (PMID 33495418, 2021). "Treatment of fLfs or mice having bleomycin- or Ad-TGF-β1–induced lung fibrosis with CSP/CSP7 reduced the expression of glycolytic enzymes and HIF-1α." (PMID 32841217, 2020). "Raltegravir ameliorated pulmonary fibrosis by reducing the pathology score, collagen deposition, and expression of α-smooth muscle actin, NLRP3, HMGB1, TLR4, inhibitor of kappa B, p-NF-κB, HIF-1α, collagen I, and collagen III." (PMID 31481891, 2019). "Our results show that HIF-1α and CHOP proteins were both detected in hyperplastic AECs observed in IPF patients’ lung biopsies and in bleomycin-induced pulmonary fibrosis in mice as well as in AECs from rat exposed to acute hypoxia." (PMID 30560874, 2018). "Hypoxia‐inducible factor‐1α (HIF‐1α) and epithelial‐mesenchymal transition (EMT) are involved in the progression of pulmonary fibrosis." (PMID 26781174, 2016). "Thus, HIF‐1α might be a target for the treatment of PQ poisoning‐induced early pulmonary fibrosis." (PMID 26781174, 2016).
pulmonary fibrosis (continued). "Our study observed elevation of HIF-1α and ZEB1 protein levels in both the fibrotic lung tissues in vivo and hypoxic pneumocytes in vitro, which correlated with EMT activation and lung fibrosis." (PMID 26819949, 2015). "Cyclosporin A and HIF-1α inhibitors (HIFi) inhibit TGF-β1-induced fibroblast-to-myofibroblast transition, reducing expression levels of α-SMA and fibronectin, and dedifferentiating myofibroblast-like cells (MyoLCs) from pulmonary fibrosis patients." (PMID 39026235, 2024). "Given both hypoxia and TGF-β signaling pathways are activated in pulmonary fibrosis, HBO may inhibit HIF-1α expression induced by both hypoxia and TGF-β." (PMID 34150851, 2021). "Mitigation of lung fibrosis by CSP/CSP7 will alleviate tissue hypoxia, which could also inhibit HIF-1α and glycolysis in vivo." (PMID 32841217, 2020). "The mechanism may function through miR‐210‐mediated repression of RUNX3, which further decreases the hydroxylation activity of PHD2, enhances the stability of HIF‐1α, and promotes PQ‐induced EMT, aggravating the progression of pulmonary fibrosis." (PMID 28699703, 2017). "Thus, this feed-forward loop involved in lactic acid, TGF-β, HIF-1α, and LDH strengthens aerobic glycolysis and TGF-β-induced fibroblast differentiation into myofibroblasts in idiopathic pulmonary fibrosis." (PMID 29186898, 2017). "Our research aimed to determine whether the regulation of HIF‐1α in EMT occurs via the Snail and β‐catenin pathways in PQ poisoning‐induced pulmonary fibrosis." (PMID 26781174, 2016). "Our study showed that HIF‐1α might modulate EMT via the Snail and β‐catenin pathways in PQ poisoning‐induced early pulmonary fibrosis." (PMID 26781174, 2016). "In addition, the findings revealed that hypoxia‐inducible factor‐1 alpha (HIF‐1α) serves as a crucial metabolic regulator in the transition from FAO to glycolysis, thereby playing a significant role in ECM deposition in silica‐induced pulmonary fibrosis." (PMID 39721015, 2025). "In this study, we explored the roles of Hif-1α and its downstream molecule EGFR in pulmonary fibrosis mice and the APD group, suggesting that APD might regulate ferroptosis by inhibiting the Hif-1α-EGFR pathway, thereby alleviating pulmonary fibrosis." (PMID 38584671, 2024). "Moreover, CsA and HIF-1α inhibitors (HIFi) can reduce the expression levels of α-SMA and fibronectin, inducing dedifferentiation in myofibroblast-like cells (MyoLCs) derived from pulmonary fibrosis patients." (PMID 39026235, 2024). "It has been reported that HIF-1α can activate PDK1, leading to increased phosphorylation of PDH and increased lactate production, thereby inducing myofibroblast differentiation, and specific knockout of HIF-1α in fibroblasts can alleviate bleomycin-induced pulmonary fibrosis in mice." (PMID 38203486, 2023). "Moreover, the dynamic change in the HIF-1α expression, which first increased and subsequently decreased, suggested its involvement in hypoxia and inflammatory damage observed in the early stages of BLM-induced pulmonary fibrosis." (PMID 33495418, 2021). "Taken together, these results suggest that localized hypoxia of the alveolar milieu and expression of HIF-1α could promote UPR pathways, CHOP expression and apoptosis in AECs, therefore contributing to alveolar cell dysfunction and finally promoting lung fibrosis." (PMID 30560874, 2018). "However, the relationship among HIF‐1α, Snail and β‐catenin in PQ poisoning‐induced pulmonary fibrosis is not clear." (PMID 26781174, 2016). "However, the relationship among HIF‐1α, Snail and β‐catenin has not been extensively researched in pulmonary fibrosis." (PMID 26781174, 2016).
lymph node metastasis (86 papers, 2003 to 2026). "In laryngeal cancer, HIF-1α overexpression has been associated with lymph node metastasis, a high T-stage and poor survival." (PMID 38474362, 2024). "Concordant with the association between HIF-1α expression and lymph node metastasis, high mRNA HIF-1α expression was also associated with tumour size and pathological stage (p < 0.05)." (PMID 34298636, 2021). "In ESCC patients, a upregulated HIF-1α expression is associated with lymph node metastasis and resistance to radiotherapy." (PMID 34249682, 2021). "Our findings demonstrate an association of HIF-1α overexpression with tumor size, tumor stage, lymph node metastasis, and overall survival." (PMID 28521842, 2017). "For PFS a significant association was found for TNM-stage, presence of lymph node metastasis, heritability, HIF-1α, necrosis and Glut-1." (PMID 28404916, 2017). "In our meta-analysis, higher HIF-1α expression was found to be associated with increased risk of lymph node metastasis, higher FIGO stage, higher histological grade, and lower 5-year OS and DFS rate." (PMID 25993275, 2015). "The expression levels of STAT3, p-STAT3 and HIF-1α, VM, status of lymph node metastasis and tumor differentiation degree were associated with the overall survival time of patients with GAC (P<0.05)." (PMID 24959290, 2014). "HIF-1α overexpression was closely associated with clinicopathological parameters, including histological differentiation, T stage and lymph node metastasis." (PMID 23251251, 2013). "Moreover, high HIF-1α expression predicts poorer prognosis and is associated with tumor grade, lymph node metastasis, and myometrial infiltration in EC patients." (PMID 39668821, 2024). "High expression of HIF-1a was associated with lymph node metastasis." (PMID 37036874, 2023). "As POI type IV is associated with lymph node metastasis, the predominance of highly expressing HIF-1α cases in the POI type IV group may disclose an indirect association between HIF-1α expression and neck lymph node metastasis." (PMID 37445908, 2023). "Only in combined analysis, patients with ≥ 2 variant alleles of all 4 polymorphisms in VHL and HIF1A genes (VHL rs779805, HIF1A rs11549465, HIF1A rs11549467, HIF1A rs2057482) in their study were significantly associated with localized clinical stage and less frequency of lymph node metastasis." (PMID 38115281, 2023). "An overview of meta-analyses studies showed that HIF-1α expression was significantly associated with lymph node metastasis and the survival rate in a great number of malignancies, including osteosarcoma, lung, breast, esophageal, gastric, colorectal, pancreatic, and ovarian cancer." (PMID 35890106, 2022). "Increasing evidence has revealed that hypoxia linked HIF-1α overexpression is found to be associated with lymph node metastasis and pathologic stage, poor EC differentiation and increased depth of tumor invasion, disease-free survival rate, and initial response to concurrent chemoradiotherapy." (PMID 34081626, 2021). "Furthermore, MMP-13 levels were closely associated with HIF-1α expression (r = 0.679, P < 0.001), lymph node metastasis, clinical stage (all P < 0.05) and poor prognosis in NPC patients (P < 0.01)." (PMID 29515112, 2018). "As G1790A enhances the stability and trans-activating capacity of HIF-1α, it is possible that it may also affect the risk of lymph node metastasis." (PMID 24808762, 2014). "The expression of HIF-1α may be associated with lymph node metastasis." (PMID 23599780, 2013). "In this study, we aim to evaluate the relationship between the SUVmax, GLUT1, and HIF-1α expression with primary tumor size, histological type, lymph node metastases, and patient survival." (PMID 37445752, 2023). "Forty studies investigated the association of HIF-1α expression with OS, ten with DFS, thirty-four with lymph node metastasis (LNM), seventeen with distance metastasis (DM), twenty-nine with TNM stage, and nineteen studies with tumor size." (PMID 35845307, 2022).